BRCA2 (BRCA2 DNA repair associated)
Diseases named in the same sentence as BRCA2 in open-access papers (continued):
Sharing a sentence is not in itself a finding about the gene and the disease.
breast cancer (continued). "CHEK2: After BRCA1 and BRCA2, this was the first breast cancer moderate risk gene to be identified after observing a common deletion (1100delC) in non-BRCA breast cancer families." (PMID 34439109, 2021). "Our data suggest that a hypomorphic BRCA2 allele retaining 37–54% of normal HRR function can prevent FA clinical phenotype, but not the early onset of breast cancer and severe hypersensitivity to chemotherapy." (PMID 34504103, 2021). "In a large cohort comprising 1554 Brazilian breast cancer patients referred for genetic testing at a single clinical diagnostic laboratory in Brazil, 9.84% were found to be BRCA1 or BRCA2 mutation carriers independent of age." (PMID 34287479, 2021). "Recent studies from the United Kingdom and Australia have shown that multigene testing (BRCA1, BRCA2 and PALB2, and BRCA1 and BRCA2, respectively) for all breast cancer patients would be cost-effective when compared with current eligibility criteria based on personal and family-history testing." (PMID 33113089, 2021). "Ten-year cumulative contralateral Breast Cancer (CBC) risks were 21.1% for BRCA1, 10.8% for BRCA2 mutation carriers and 5.1% for non-carriers." (PMID 34356066, 2021). "The patient had no identifiable germline breast cancer predisposition variants, in concordance with earlier clinical testing for BRCA1 and BRCA2 germline mutations." (PMID 34711268, 2021). "The Consortium of Investigators of Modifiers of BRCA1/2 (CIMBA) reported a ratio of 3.5:1 excess of BRCA1 CNVs compared to BRCA2, among 18,435 breast cancer cases with BRCA1 PVs and 11,351 with BRCA2, ascertained from 69 centers in 49 countries on 6 continents." (PMID 34413315, 2021). "Among all patients with breast cancer without selection bias, the BRCA1/2 mutation retention rate was 4.2–6.1% (BRCA1: 1.45–3.7%, BRCA2: 2.4–3.5%)." (PMID 32862296, 2021). "Thus, different ovarian cancer cluster regions (OCCRs) and breast cancer cluster region (BCCRs) can be formulated for both the BRCA1 and BRCA2 genes." (PMID 34680878, 2021). "Although PALB2 encodes a protein involved in DNA double-strand break repair carried out by BRCA2, tailored therapies for breast cancer patients carrying PVs in genes other than BRCA1/2 have not yet been established." (PMID 33718150, 2021). "Interestingly, while in Belgian and Czech breast cancer patients the frequency of BRCA1 germline PV is higher than BRCA2, BRCA2 PV prevails in PDAC patients in both populations." (PMID 34503238, 2021). "MBC patients, who were carriers of BRCA2:c.7806-2A > G, did not experience higher incidence of other cancers, excluding non-melanoma skin cancer and contralateral breast cancer (22.2% vs. 23.6%, p = 1.0)." (PMID 33891299, 2021). "Also, in MCF-7 breast cancer cell lines, PTEN, pRB, and BRCA2 are upregulated with 2.95, 2.21, and 2.195 folds, respectively." (PMID 34680491, 2021). "Despite guidelines that recommend genetic testing for patients at increased risk of carrying a pathogenic variant in a breast cancer gene (e.g. BRCA1, BRCA2, CHEK2, PALB2, ATM) not all eligible patients are referred for genetic testing." (PMID 33933926, 2021). "We did not evaluate the effect of medical ovarian suppression on breast cancer survival in the BRCA2 carrier population to see if medical ovarian suppression is a viable alternative to oophorectomy." (PMID 33597716, 2021). "For the well-known breast cancer biomarkers, only HER2 status was statistically significantly associated with high risk (p = 0.010), but not others (BRCA1, BRCA2, ER, PR, p > 0.05)." (PMID 34650974, 2021).
breast cancer (continued). "For instance, among two cohorts of breast cancer patients, the TMB was 2.0 to 2.6 times higher in patients with a BRCA1 or BRCA2 mutation as compared to those without a BRCA mutation." (PMID 34067105, 2021). "It has been also demonstrated that some sporadic breast cancers harbor defects in the HR and FA pathway, in the absence of a germline BRCA1 or BRCA2 mutation, a condition referred as BRCAness." (PMID 33808562, 2021). "In Poland, 20 founder mutations in BRCA1, BRCA2, CHEK2, PALB2, NBN, RECQL are responsible for the majority of hereditary breast cancer cases in women, but the utility this genes panel has not been tested in men." (PMID 34461861, 2021). "The new technologies discussed here allow a similar course of action for the much larger set of families with breast cancer history who are not carriers of BRCA1 or BRCA2." (PMID 34440279, 2021). "Although risks with estrogen therapy and breast cancer are well known, patients with a familial history or with breast cancer susceptibility genes (BRCA1 and BRCA2) do not have an additional risk with CHC." (PMID 32397460, 2020). "In breast cancer cases, four BRCA1 heterozygotes and 17 BRCA2 heterozygotes were identified." (PMID 32300229, 2020). "In the case of breast cancer, CD44 and BRCA2 showed a strong positive correlation (p = 0.003)." (PMID 32610620, 2020). "Within breast cancers, TMB was higher for BRCA1 and BRCA2 germline mutation carriers relative to non-carriers and was also elevated in BL1 subtype." (PMID 32164626, 2020). "BRCA1 and BRCA2 mutated breast cancers have been reported to have different molecular characteristics from each other, for example, a correlation between TNBC and BRCA1 but not BRCA2." (PMID 32455662, 2020). "Two high-penetrance breast cancer genes, BRCA1 and BRCA2, are thought to be responsible for only 13% of MBC, and multiple genetic factors remain unknown." (PMID 32185139, 2020). "We did not observe any survival benefit in BRCA1/BRCA2 carriers with HER-2 positive or ER/PR-positive HER-2 negative breast cancers (non-TNBC)." (PMID 32341426, 2020). "One BRCA2 mutation carrier who was homozygous for the minor RAD52 allele had breast cancer, and three homozygotes did not have breast cancer." (PMID 32255263, 2020). "(D) Box-plots of HR (BRCA1, BRCA2, ATR) and NHEJ (PRKDC, XRCC5, XRCC6) protein expression levels (ratio to pool) in the different groups of breast cancer cell lines according to AZD1775 response characteristics (recovering-basal, sensitive-basal and recovering-luminal)." (PMID 32628111, 2020). "Contralateral breast cancer is also increased in BRCA1 and BRCA2 PV carriers." (PMID 32045981, 2020). "Initial clinical testing (BRCA1, BRCA2 and PALB2) in a 40-year-old female with unilateral breast cancer did not detect any pathogenic variants." (PMID 32884827, 2020). "In other studies performed in China, higher pathogenic variant frequencies ranging from 0.54 to 1.6% were observed in BRCA1 and BRCA2 negative early-onset and/or familial breast cancer cases." (PMID 33342430, 2020). "The 10-year cumulative contralateral breast cancer risk following the initial breast cancer diagnosis was 21.1% for BRCA1, 10.8% for BRCA2 and 5.1% for non-carriers." (PMID 31935898, 2020). "Because of bilateral breast cancer, she underwent BRCA1 and BRCA2 testing." (PMID 32455662, 2020).
breast cancer (continued). "Within the group of 46 women diagnosed with TNBC between 45 and 60 years of age but without a significant family history of breast cancer, three (6.5%) harbored mutations in ATM (n = 1), BAP1 (n = 1), or BRCA2 (n = 1)." (PMID 33302456, 2020). "Because her grandmother had a history of breast cancer, she underwent BRCA1 and BRCA2 testing." (PMID 32455662, 2020). "In contrast, this has not been reported in BRCA2 carriers, who predominately develop luminal breast cancer." (PMID 32022473, 2020). "The breast cancer surveillance guidance for BRCA mutation carriers from the NABON specifies that screening for ovarian cancer in BRCA1 and BRCA2 mutation carriers is not recommended." (PMID 32655641, 2020). "A cohort study has shown improved overall and breast cancer-specific mortality rates in BRCA1 mutation carriers, while for BRCA2, survival rates were not significantly different after a median follow-up for 10.3 years." (PMID 32655641, 2020). "However, most ovarian and breast cancers, and nearly all other types of cancer, have normal BRCA1 and BRCA2; and even in BRCA1/2-mutant tumors, responses to PARPi are heterogeneous and initially responsive cancers eventually develop PARPi resistance." (PMID 32029902, 2020). "A more recent CMT study has shown that BRCA2 messenger RNA expression decreases in adenomas but increases in mammary carcinoma lymph node metastases when compared with non-neoplastic mammary epithelium." (PMID 32411603, 2020). "Levels of BRCA2 mRNA and protein should commensurate with the status of the cells; they are upregulated in proliferating breast cancer (BC) cells but repressed in non-dividing (G0/G1) cells due to its toxicity." (PMID 31987042, 2020). "Indeed, inactivation of BRCA1, BRCA2, PALB2, FAM175A, and BARD1 are synthetic lethal with PARG depletion in MCF7 breast cancer cells due to disruption of HR-mediated DDR." (PMID 30889383, 2019). "Expression of immunostimulator and immunoinhibitor molecules, other than PD-L1 and PD-1, respectively, were generally increased in BRCA1-deficient breast cancers, but not in BRCA2-deficient breast cancers, compared to BRCA-proficient breast cancers." (PMID 31022191, 2019). "While truncating variants in BRCA2 and PALB2 confer a substantial risk of breast cancer, our study suggests that truncating FANCC variants do not confer a comparable risk." (PMID 31467304, 2019). "In addition, the exposure of breast cell lines to ω-3 PUFA (EPA and DHA) was related to the increase in the expression of two breast cancer suppressor genes, namely BRCA1 and BRCA2." (PMID 31505792, 2019). "Unlike breast cancer, which has a well-established association with mutations in the BRCA1 and BRCA2 genes, there remains insufficient evidence linking genetic variations to the development of PT." (PMID 31195364, 2019). "Here we used the results of genetic testing of women diagnosed with breast cancer, but who did not have variants in BRCA1 and BRCA2 genes." (PMID 31569399, 2019). "The well-known breast cancer specific germline mutations in BRCA1 (185delAG; Chr17: 43124030–43124031 and 5382insC; Chr17: 43057065) and BRCA2 (6174delT; Chr13: 32340301) were not amongst the variants identified in either the GBM cohort or the TCGA-GBM cohort." (PMID 32082376, 2019).
breast cancer (continued). "Furthermore, 30 μM resveratrol treatment of breast cancer cell lines MCF7, MDA-MB 231, and HBL 100 for two days resulted in an observed surge in BRCA1 and BRCA2 mRNA." (PMID 31505792, 2019). "It is interesting that heterozygous mutations in other genes in this pathway (i.e., BRCA1, BRCA2, CHEK2, NBN, ATM) predispose to breast cancer, but a heterozygous mutation in BLM does not appear to be pathogenic for breast cancer." (PMID 31614901, 2019). "A 35-year-old woman with a BRCA2 mutation developed IDC that was ER-, progesterone receptor (PgR)-negative, and HER2-negative, as a primary breast cancer during surveillance, 2 years after receiving her genetic testing results." (PMID 30980249, 2019). "While both BRCA1- and BRCA2-deficient breast cancers shared similar genomic features, only BRCA1-, but not BRCA2-deficient breast cancers, were associated with immune signatures." (PMID 31022191, 2019). "Our goal was to characterize BRCA1 and BRCA2 germline mutations in a group of very young Brazilian patients and to identify somatic mutations in luminal HER2 negative breast cancer." (PMID 29854292, 2018). "On the other hand, medullary phenotype without family anamnesis did not have any class 4 or 5 somatic mutations in the BRCA2 gene, pointing out to the role of the BRCA1 gene only in breast cancer with medullary features." (PMID 29453630, 2018). "We performed BRCA1/2 testing by next-generation sequencing in clinically sporadic breast cancer patients with medullary like breast cancer and without known BRCA1 and BRCA2 mutations at presentation." (PMID 29453630, 2018). "We identified 16 qualified studies from 527 publications with 46,870 breast cancer patients including 868 BRCA1 mutations (BRCA1Mut) carriers, 739 BRCA2 mutations (BRCA2Mut) carriers, and 45,263 non-carriers." (PMID 30186165, 2018). "For first breast cancers, the average age of onset in the BRCA1- and BRCA2-positive groups (90 and 98 cases) and BRCA-negative group (588 cases) was 40.2 years (95% confidence interval (CI) 38.15–42.25), 41.7 years (95% CI 39.71–43.70), and 45.4 years (95% CI 44.54–46.26), respectively." (PMID 29176636, 2018). "Four genes (six associations: BRCA1, BRCA2, and ANK2 in ovarian cancer, BRCA1, BRCA2, and ATM in breast cancer) were significant in at least one individual cancer type (FDR = 0.2, referred to as ‘individual cancer ALFRED genes’) and all four genes were also significant in the pan-cancer analysis." (PMID 29973584, 2018). "Five patients had a family history of breast cancer, but none of the four patients who underwent genetic testing had germline BRCA1 or BRCA2 gene mutations." (PMID 29304773, 2018). "Data for the 5,949 first-degree relatives was utilized to obtain estimates of breast cancer penetrance in mutation carriers (230 from BRCA1 carrier relatives, 309 from BRCA2 carrier relatives and 5,410 from non-carrier relatives)." (PMID 29861850, 2018). "First, for Nigerian women, BRCA1 and BRCA2 have a major effect on breast cancer incidence both because the ORs for BRCA1 and BRCA2 are extremely high (> 20 for BRCA1; > 10 for BRCA2) and because 11% of patients carry a damaging mutation in one of these genes (7.0% in BRCA1; 4.1% in BRCA2)." (PMID 30130155, 2018). "Very few studies, if any, have been carried out with comprehensive analysis of BRCA1 and BRCA2 in truly unselected breast cancer patients in high-incidence countries without strong founder mutations." (PMID 29164420, 2018). "Third, BRCA2 reversion events in breast cancer may contribute to resistance in platinum and/or PARP inhibitor-treated BRCA2 carriers." (PMID 29093439, 2017).
breast cancer (continued). "Moreover, the median frequency of DMD alterations in sporadic breast cancer was higher than the median frequency for BRCA genes in the same tumors (3.95% vs 1.95% and 3.40% for DMD, BRCA1 and BRCA2, respectively)." (PMID 27391342, 2017). "Our study confirmed BRCA2 p.Ile3412Val is presented in >2% of unaffected women and is likely benign, and BRCA2 p.Ala1996Thr which is predicted to be likely pathogenic by in-silico models is presented in 2% of healthy Indian women suggesting that it may not be associated with breast cancer risk." (PMID 28222693, 2017). "Despite the family history of breast cancer, no known pathogenic BRCA1 or BRCA2 germline variants were identified." (PMID 28487881, 2017). "Consanguinity can lower breast cancer risk (BCR) as homozygosis of mutated DNA-repair genes like BRCA1 and BRCA2, being incompatible with life, are not transmitted to the next generation." (PMID 29157216, 2017). "This dataset contained 12 BRCA1- and 1 BRCA2-mutated hereditary breast tumors, 8 BRCAx (non-BRCA1/2 mutations, donated as non-BRCA) hereditary breast tumors, 14 sporadic breast cancer samples and 6 normal samples." (PMID 29146938, 2017). "We performed a comprehensive analysis of BRCA1 and BRCA2 genes by Sanger sequencing and multiplex ligation‐dependent probe amplification (MLPA) to detect large rearrangements in patients from 18 families, which met the criteria for hereditary breast cancer." (PMID 28944232, 2017). "The preeminent knowledge accessible to date is based on a joint investigation of 22 researches, 11 which established that the prevalence of breast cancer is 65% at 70 years of age in women who acquired a BRCA1 gene and 45% in those women who are carriers of BRCA2 genes." (PMID 28969709, 2017). "Hope and optimism have also been found as facilitating adaptation to an increased familial breast cancer risk, when this has been studied in women from high-risk families with and without a BRCA1/BRCA2 mutation." (PMID 28780755, 2017). "PM yields a risk reducing effect of more than 90-100% in healthy BRCA1 and BRCA2 mutation carriers and PBSO decreases breast cancer risk in BRCA mutation carriers without prior breast cancer approximately by 50%." (PMID 28977823, 2017). "The HR of breast cancer was 5.90 (95% CI 2.01 to 17.33) for BRCA1 and HR = 2.55 (95% CI 0.49 to 13.13) for BRCA2 mutation carriers compared to non-carriers." (PMID 28680148, 2017). "Despite bilateral and early-onset breast cancer in the family, this patient tested negative for high-penetrance mutations in the BRCA1 and BRCA2 genes." (PMID 28241424, 2017). "The aim of our study is to compare the clinicopathological characteristics between Moroccan breast cancers associated or not with BRCA1 and BRCA2 mutations." (PMID 27129401, 2016). "Sequencing and further analysis of the libraries constructed from 6 cases with strong family histories of breast cancer who previously tested negative for mutations in BRCA1 and BRCA2 are undergoing." (PMID 27294413, 2016). "Nevertheless, mammary-specific inactivation of either the Brca1, Bard1, or Brca2 gene readily induces mammary tumors despite the fact that mice lacking expression of these genes also die during early embryogenesis." (PMID 27058754, 2016). "We also predicted that breast cancer would occur in 41 women (range 36–62) incorrectly identified with no pathogenic mutations and in 12,460 women without BRCA1 or BRCA2 mutations." (PMID 27252788, 2016).